RAB3IP (RAB3A interacting protein)
Description:
Guanine nucleotide exchange factor (GEF) which may activate RAB8A and RAB8B. Promotes the exchange of GDP to GTP, converting inactive GDP-bound Rab proteins into their active GTP-bound form. Mediates the release of GDP from RAB8A and RAB8B but not from RAB3A or RAB5. Modulates actin organization and promotes polarized transport of RAB8A-specific vesicles to the cell surface. Together with RAB11A, RAB8A, the exocyst complex, PARD3, PRKCI, ANXA2, CDC42 and DNMBP promotes transcytosis of PODXL to the apical membrane initiation sites (AMIS), apical surface formation and lumenogenesis. Part of the ciliary targeting complex containing Rab11, ASAP1, RAB3IP and RAB11FIP3 and ARF4 that promotes RAB3IP preciliary vesicle trafficking to mother centriole and ciliogenesis initiation.
Synonyms: RABIN8; RABIN3; FLJ22548
Tractability: Small molecule: a structure with a bound ligand is known. PROTAC: ubiquitination databases record sites on it; its protein half-life has been measured.
Gene: Protein-coding gene on chromosome 12 (69,738,860 to 69,823,204, forward strand). Ensembl gene ENSG00000127328.
Subcellular location: Cytoplasm; Nucleus; Cytoplasm, cytoskeleton; Cell projection, lamellipodium; Vesicle; Cytoplasm, cytoskeleton, microtubule organizing center, centrosome
Subcellular location (Human Protein Atlas): Nucleoplasm; Centrosome; Cytosol
Pathways (Reactome):
Organelle biogenesis and maintenance: Anchoring of the basal body to the plasma membrane; BBSome-mediated cargo-targeting to cilium; VxPx cargo-targeting to cilium
Vesicle-mediated transport: RAB GEFs exchange GTP for GDP on RABs
Gene Ontology:
Molecular function: guanyl-nucleotide exchange factor activity; protein binding; GTPase binding
Biological process: protein targeting to membrane; ciliary transition zone assembly; cilium assembly; negative regulation of filopodium assembly
Cellular component: centrosome; cytoplasm; cytosol; nucleoplasm; nucleus; vesicle; cytoskeleton; lamellipodium; perinuclear region of cytoplasm; proximal dendrite
Genetic constraint (gnomAD): Loss-of-function variants: 16 observed, 23.72 expected, observed/expected ratio (o/e) 0.67, 90% interval 0.46 to 1.02. The upper end of that interval is the gene's LOEUF score, 1.02, which puts it in group 4 of 6, group 1 being the genes least tolerant of losing a copy. Missense variants: 326 observed, 352.92 expected, observed/expected ratio (o/e) 0.92, 90% interval 0.84 to 1.01. Synonymous variants: 131 observed, 132.88 expected, observed/expected ratio (o/e) 0.99, 90% interval 0.86 to 1.14.
Homologues: Orthologues: macaque RAB3IP (99% identical), dog RAB3IP (97% identical), pig RAB3IP (97% identical), rabbit RAB3IP (91% identical), rat Rab3ip (91% identical), mouse Rab3ip (91% identical), chimpanzee RAB3IP (82% identical), guinea pig RAB3IP (82% identical), tropical clawed frog rab3ip (78% identical), zebrafish rab3ip (67% identical), Caenorhabditis elegans F54C9.11 (26% identical). Paralogues in human: RAB3IL1 (44% identical).
Diseases named in the same sentence as RAB3IP in open-access papers:
RAB3IP is named in the same sentence as 17 diseases in open-access papers, as found by Europe PMC text mining. Sharing a sentence is not in itself a finding about the gene and the disease. The quoted sentences say what the papers report.
gastric cancer (5 papers, 2020 to 2025). A primary or metastatic malignant neoplasm involving the stomach. "It has been reported that miRNA-532 can reverse the inhibitory effect of Rab3IP on the autophagy signaling pathway in gastric cancer." (PMID 37403096, 2023). "Moreover, its effector protein RAB3IP is involved in insulin exocytosis from pancreatic β cells and promotes cell proliferation via inhibiting autophagy in gastric cancer." (PMID 32759795, 2020). "RAB3IP, RanGAP1, and KIAA1244 are host genes of exosomal circRNA which exhibited more than two-fold differences in gastric cancer." (PMID 34249673, 2021). "Among them, RAB3A interacting protein (RAB3IP), Ran GTPase-activating protein 1 (RanGAP1), and KIAA1244 exhibited a fold change >2, indicating significantly high expression in gastric cancer." (PMID 34249673, 2021). "For instance, RAB3A interacting protein (Rab3IP) is a Rab-specific GEF, and the activation of Rab proteins, including RAB3A and RAB8, has been considered a tumor-specific marker in colorectal cancer, gastric cancer, and pancreatic cancer." (PMID 37158817, 2023).
colorectal cancer (2 papers, 2023 to 2025). A primary or metastatic malignant neoplasm that affects the colon or rectum. "To further clarify the role of RAB3IP in colorectal cancer, first, we examined the expression of RAB3IP in a variety of colorectal cancer cells." (PMID 40657366, 2025). "We systematically analyzed the prognostic value of transcription levels of SFs in colorectal cancer (CRC) and found that RAB3A interacting protein (RAB3IP), programmed cell death 4 (PDCD4), golgin B1 (GOLGB1), and neuregulin 4 (NRG4) as the most predictive markers for the prognosis of CRC." (PMID 40657366, 2025).
Lymph node metastasis (1 paper, 2025). "We observed that high levels of RAB3IP expression were significantly associated with the Lymph node metastasis of CRC patients." (PMID 40657366, 2025).
metastatic colorectal cancer (1 paper, 2020). "In metastatic colorectal cancer, the inadvertent activation of evolutionarily methylation-silenced genes MET, RAB3IP and CHRM3 proto-oncogenes have been identified." (PMID 32905102, 2020).
type 2 diabetes mellitus (1 paper, 2019). A type of diabetes mellitus that is characterized by insulin resistance or desensitization and increased blood glucose levels. "Misregulation of RAB3IP in islets from diabetic donors tentatively supports a direct link between cilia/basal body dysfunction, vesicle trafficking, and Type 2 Diabetes mellitus; still, further studies are warranted to more firmly establish such a link." (PMID 31831727, 2019).
tumor (5 papers, 2004 to 2025). "Based on the concordant evidence of tumor-specific overexpression and strong survival association, RAB3IP was prioritized for functional characterization." (PMID 40657366, 2025). "Additionally, tissue microarray data from the Human Protein Atlas database indicated that RAB3IP is upregulated in tumor tissues, suggesting its potential role in tumor progression." (PMID 40657366, 2025).
cancer (2 papers, 2015 to 2025). A tumor composed of atypical neoplastic, often pleomorphic cells that invade other tissues. "After comparing the expression of four splicing factors in cancer tissues with normal tissues as well as OS analysis, it is strongly indicated that only RAB3IP demonstrates a significant positive correlation with favorable prognosis." (PMID 40657366, 2025). "Mutations in other cancer‐associated genes such as MAGI3, TSC1, PTPN4, RAB3IP, and RYR1 were also identified." (PMID 26432421, 2015). "Moreover, by the Gene Set Enrichment Analysis (GSEA), we demonstrated that the RAB3IP was correlated to Cell Cycle, WNT pathway and Spliceosome in cancer." (PMID 40657366, 2025).
RAB3IP also shares sentences with these, for which no sentence is quoted: ciliopathies (2 papers); infection (2); Parkinson disease (2); bladder tumors (1); Blindness (1); Leber congenital amaurosis (1); osteoporosis (1); pancreatic cancer (1); Parkinson’s (1); retinal degeneration (1).